CLSTN3 (calsyntenin 3)
Description:
Postsynaptic adhesion molecule that binds to presynaptic neurexins to mediate both excitatory and inhibitory synapse formation. Promotes synapse development by acting as a cell adhesion molecule at the postsynaptic membrane, which associates with both neurexin-alpha and neurexin-beta proteins at the presynaptic membrane. Regulates the balance between excitatory and inhibitory synapses by inhibiting formation of excitatory parallel-fiber synapses and promoting formation of inhibitory synapses in the same neuron (By similarity). May also be involved in ascorbate (vitamin C) uptake via its interaction with SLC23A2/SVCT2. Complex formation with APBA2 and APP, stabilizes APP metabolism and enhances APBA2-mediated suppression of beta-APP40 secretion, due to the retardation of intracellular APP maturation (Probable). [Isoform CLSTN3beta]: Adipose-specific isoform that plays a key role in adaptive thermogenesis. Facilitates the efficient use of stored triglyceride by promoting multilocular morphology of thermogenic adipocytes: acts by inhibiting the activity of CIDEA and CIDEC on lipid droplets, thereby preventing lipid droplet fusion and facilitating lipid utilization. May also participate in adaptive thermogenesis by promoting sympathetic innervation of thermogenic adipose tissue: acts by driving secretion of neurotrophic factor S100B from brown adipocytes, stimulating neurite outgrowth from sympathetic neurons.
Synonyms: KIAA0726; CSTN3; CDHR14; alcbeta
Tractability: Antibody: UniProt places it where antibodies can reach, with medium confidence; UniProt predicts a signal peptide or a membrane-spanning region; its Gene Ontology location is reachable by antibodies, with medium confidence. PROTAC: UniProt records ubiquitination sites on it; its protein half-life has been measured.
Gene: Protein-coding gene on chromosome 12 (7,128,077 to 7,158,945, forward strand). Ensembl gene ENSG00000139182.
Subcellular location: Postsynaptic cell membrane; Endoplasmic reticulum membrane; Golgi apparatus membrane; Cell projection, dendrite; Lipid droplet (Isoform CLSTN3beta)
Gene Ontology:
Molecular function: cell-cell adhesion mediator activity; neurexin family protein binding; protein binding; calcium ion binding
Biological process: homophilic cell-cell adhesion; positive regulation of synapse assembly; positive regulation of synaptic transmission
Cellular component: cell surface; endoplasmic reticulum membrane; Golgi membrane; lipid droplet; postsynaptic density membrane; postsynaptic membrane; dendrite; membrane
Genetic constraint (gnomAD): Loss-of-function variants: 36 observed, 93.6 expected, observed/expected ratio (o/e) 0.38, 90% interval 0.29 to 0.51. The upper end of that interval is the gene's LOEUF score, 0.51, which puts it in group 2 of 6, group 1 being the genes least tolerant of losing a copy. Missense variants: 1,084 observed, 1,293.2 expected, observed/expected ratio (o/e) 0.84, 90% interval 0.8 to 0.88. Synonymous variants: 481 observed, 512.06 expected, observed/expected ratio (o/e) 0.94, 90% interval 0.87 to 1.01.
Homologues: Orthologues: chimpanzee CLSTN3 (98% identical), macaque CLSTN3 (98% identical), pig CLSTN3 (97% identical), rabbit CLSTN3 (97% identical), guinea pig CLSTN3 (96% identical), dog CLSTN3 (96% identical), mouse Clstn3 (96% identical), rat Clstn3 (96% identical), tropical clawed frog clstn3 (62% identical), zebrafish clstn3 (62% identical), Drosophila melanogaster Cals (28% identical), Caenorhabditis elegans casy-1 (26% identical). Paralogues in human: CLSTN1 (51% identical), CLSTN2 (47% identical).
Diseases named in the same sentence as CLSTN3 in open-access papers:
CLSTN3 is named in the same sentence as 21 diseases in open-access papers, as found by Europe PMC text mining. Sharing a sentence is not in itself a finding about the gene and the disease. The quoted sentences say what the papers report.
Obesity (5 papers, 2020 to 2025). Accumulation of substantial excess body fat. "In this context, high levels of Camp and Lcn2 are associated with muscle degeneration and can be implicated in Duchenne muscular dystrophy; Clstn3 is associated with obesity risk; and Irf4 knockout mice show better exercise capacity." (PMID 40002138, 2025). "CLSTN3 gene polymorphism led to dysfunction in white adipose tissue and was associated with obesity that was closely related to CRC risk." (PMID 37726845, 2023). "We have previously shown that an intronic variant rs7296261 at the CLSTN3 locus associated with obesity risk and high CLSTN3 expression in human adipose tissue." (PMID 39872858, 2023). "In contrast to Clstn3b global knockout mice, which show obesity due to reduced sympathetic innervation of BAT, Clstn3 global knockout mice show reduced body mass due to improved leptin sensitivity and increased energy expenditure." (PMID 32382066, 2020). "Similar to cold adaptation, the expression of Clstn3α was not affected by obesity in BAT, indicating that the β, but not the α variant of the Clstn3 gene, dynamically responds to pathological events induced by obesity in murine brown fat." (PMID 33101212, 2020).
schizophrenia (4 papers, 2017 to 2022). A major psychotic disorder characterized by abnormalities in the perception or expression of reality. "These include: VAT‐1, DAD‐1, PAQR9, BCKD, BDH, Prickle4, PP2A, RPL13A, SPRED2, KLP, FAM36A, NAB1, CLSTN3, PEDF‐R, and FZD3 (Frizzled gene previously associated with different psychopathologies, most notably Schizophrenia)." (PMID 27696737, 2017). "Although none of the genes was previously implicated in ASD, one, TRAK1 [chr3:42,244,127 (hg19), A > G], interacts with the known schizophrenia gene DISC1, and one other gene, CLSTN3 [chr12:7310,284 (hg19), G > A], was deemed likely to be pathogenic according to the ACMG guidelines." (PMID 35205252, 2022).
breast carcinoma (1 paper, 2023). "Although direct evidence on CLSTN3 protein and CRC risk is unreported, evidence from the human protein atlas has shown that high expression of CLSTN3 is favorable for prognostic of pancreatic cancer, breast cancer, and urothelial cancer." (PMID 37726845, 2023).
Intellectual disability (1 paper, 2022). "Although none of the genes habouring predicted-damaging PZMs was previously implicated in ASD, intellectual disability (ID), or other neurodevelopmental disorders, two, TRAK1 and CLSTN3, are widely expressed in the brain." (PMID 35205252, 2022).
bacterial infections (1 paper, 2022). "High expression of SPC24, NES, LOC116828075, CLSTN3, and PLAC8 was observed in the SPC24 cells of C. carbonaria, which were enriched in pathways involved in viral and bacterial infections, disease, and leukocyte transendothelial migration." (PMID 36552787, 2022).
CLSTN3 also shares sentences with these, for which no sentence is quoted: alcoholism (1 paper); atypical teratoid rhabdoid tumor (1); cancer (1); Cirrhosis (1); colon cancer (1); Duchenne muscular dystrophy (1); ependymoma (1); hepatocellular adenoma (1); infection (1); mental disorder (1); muscle degeneration (1); neurodevelopmental disorder (1); ovarian carcinoma (1); pancreatic cancer (1); rectal cancer (1); tumor (1).